VEGFD (vascular endothelial growth factor D)
Diseases named in the same sentence as VEGFD in open-access papers (continued):
Sharing a sentence is not in itself a finding about the gene and the disease.
tumor (continued). "The COL4A1‐VEGFD fusion leads to production of mature VEGFD after proteolytic processing, which may act as an autocrine growth factor for tumour cells." (PMID 33830670, 2021). "The VEGFC-VEGFR3 and VEGFD-VEGFR3 axes are considered the major drivers of tumor lymphangiogenesis." (PMID 32089745, 2020). "Indeed, recently VEGFC and VEGFD have also been reported to regulate the inflammatory tumor microenvironment, which regulates early stages of tumor growth." (PMID 31069961, 2019). "It has recently been shown that minor subclones expressing interleukin 11 (IL11) and vascular endothelial growth factor D (VEGFD) within the primary tumor can modulate the immune system in a manner that enhances polyclonal metastatic growth of otherwise non-metastatic clones." (PMID 31623163, 2019). "Alternatively, these DCs could modulate the tumor microenvironment by secreting vasculogenic factors such as vascular endothelial growth factor D (VEGF-D), platelet-derived growth factor C (PDGFC), and angiopoietin 1 (ANGPT1)." (PMID 31731454, 2019). "VEGFD-mediated tumor lymphangiogenesis plays a key role, since down-regulation of p-VEGFR-3 could block the lymph node metastasis." (PMID 26187637, 2015). "Notably, VEGFD protein expression in tumour cells was significantly elevated, and VEGFD knockdown markedly downregulated the proliferation and migration, suggesting that VEGFD released by F. nucleatum‐colonized tumour cells is crucial for tumour proliferation and migration." (PMID 40070022, 2025). "Furthermore, H&E staining showed that the TDLN metastasis rate in the shVEGFD group was 16.7% (1 of 6), which was lower than that in the control group (33.3%, 2 of 6), suggesting that lowering VEGFD expression could inhibit tumor growth and LN metastasis." (PMID 40693467, 2025). "Similarly, we inspected the VEGFD mRNA level in different tumor stages of LUAD (T1-T4)." (PMID 35941690, 2022). "Increased expression of vascular endothelial growth factors C and D (VEGFC and VEGFD) in the primary tumor is known to increase the dissemination of tumor cells to the lymph nodes, primarily through lymphangiogenesis, a process by which existing lymphatic vessels migrate towards the primary tumor." (PMID 25380524, 2014). "Here, we confirmed increased expression of VEGFA, VEGFC, and VEGFD; HEV dedifferentiation; and impaired lymphocyte homing function in tumor-draining LNs (TDLNs)." (PMID 40693467, 2025). "VEGFD can bind to the receptor VEGFR-2 on vascular endothelial cells, and the activation of VEGFR-2 promotes angiogenesis, tumor growth, and metastasis." (PMID 35537818, 2022). "In a tumour context, the lymphangiogenic growth factors VEGFC and VEGFD are produced by a variety of cell types including tumour cells, stromal cells, tumour-infiltrating macrophages and activated platelets." (PMID 33572413, 2021). "The following has been reported: (i) VEGFR3 and its ligand, VEGFC, are responsible for lymphangiogenesis; (ii) VEGFC and VEGFD contribute to tumor angiogenesis by binding to VEGFR2 and VEGFR3; (iii) VEGFR3 is expressed in the tip cells of tumor vessels." (PMID 30845711, 2019). "Expression of miR526b and miR655 in human tumour tissue was significantly correlated with lymphangiogenesis markers VEGFC, VEGFD, and LYVE-1." (PMID 31277414, 2019). "Notable downregulation of growth factors (VEGFD, FGF2, PGF, TNF-α) and cytokine IL-1A was observed in tumor cells upon treatment with 5a." (PMID 31842391, 2019). "It has been indicated that VEGFC or VEGFD can specifically bind vascular endothelial growth factor receptor-3 (VEGFR-3), as well as promote tumor lymphangiogenesis and prevent the spread of lymphatic tumor to regional lymph nodes." (PMID 27145366, 2016). "Accumulating data have also indicated that adiponectin may act as an anti-angiogenic factor in the tumor microenvironment by the decreased expression of CD31, VEGFB, and VEGFD and interleukin-12 (IL-12) activity modulation." (PMID 40227577, 2025).
tumor (continued). "VEGFD and PAK1, in particular, display strong positive correlations with bacterial load, and integrated coculture analyses confirm that MAPK signaling, mediated by VEGFD and PAK1, is a key driver of bacteria-facilitated tumor progression and metastasis." (PMID 41355895, 2025). "We found that tumor-secreted VEGFD binds to VEGFR2 on the surface of HEVs, impairs the lymphocyte homing function of HEVs, reduces the immune response of TDLNs, and provides favorable conditions for the arrival of tumor cells." (PMID 40693467, 2025). "PRAT also modulates vascular endothelial growth factor A (VEGFA), vascular endothelial growth factor D (VEGFD), Jagged 1 (JAG1), and transforming growth factor β1 (TGF-β1) activity in the tumor niche, promoting tumor angiogenesis and, consequently, cancer cell growth and metastasis." (PMID 40227577, 2025). "Moreover, the EYA3 inhibitor benzarone blocks the transcription complex formation, MMPs, VEGFD, and EGFR expression, as well as tumor growth, and neoplastic cell invasion capacity in mouse tumor xenograft and in vitro cell models." (PMID 38069210, 2023). "Furthermore, VEGFD inhibits LUAD angiogenesis by competing with VEGFA to bind to VEGFR2 in LUAD, and it also induces tumor apoptosis, which is our next research scope." (PMID 35941690, 2022). "The Assistant for Clinical Bioinformatics showed that the VEGFD mRNA level did not decline with the tumor development." (PMID 35941690, 2022). "S-nitrosylation of VEGFD in LUAD may solve this problem and provide new ideas for targeted tumor angiogenesis therapy." (PMID 35941690, 2022). "Furthermore, double staining of VEGFD and PDGFRB (a biomarker for myofibroma, myofibroblasts and pericytes) demonstrated that tumour cells expressed the two proteins." (PMID 33830670, 2021). "Furthermore, primary tumour expression of VEGFR1 and VEGFD can be used to predict significant differences in cancer specific survival in advanced renal cell carcinoma." (PMID 23577117, 2013). "Additionally, compared with normal mice, tumor-bearing mice presented substantially higher levels of VEGFA (22.3 versus 16.4 pg/mL), VEGFC (40.3 versus 31.3 pg/mL), and VEGFD (43.5 versus 33.4 pg/mL) in the peripheral blood, indicating that these factors were secreted into the TDLN." (PMID 40693467, 2025). "Moreover, we also found that MTAP may downregulate the expression of MMP2 and VEGFD in BC cells by inhibiting ODC activity, leading to the suppression of tumor angiogenesis." (PMID 35541910, 2022).
cancer (122 papers, 2003 to 2026). A tumor composed of atypical neoplastic, often pleomorphic cells that invade other tissues. "Similarly, other candidates from our DENR target list are upregulated in (and possibly causally contributing to) different cancers, such as Vascular endothelial growth factor D (VEGF-D) or Mitogen-Activated Protein Kinase 5 (MAP2K5)." (PMID 30982898, 2019). "Previous studies have documented the biological and clinical significance of VEGF family members (VEGFA, VEGFB, VEGFC, and VEGFD) in lymphangiogenesis and LN metastasis in various cancer types." (PMID 40492378, 2025). "The angiogenesis markers VEGFA, VEGFC and VEGFD were expressed in the cytoplasm of the cancer cells." (PMID 39557919, 2024). "In a lung cancer model, high levels of VEGFC (and VEGFD) promote cancer cells spread to regional lymph nodes and tumor lymphangiogenesis, facilitating lymphatic metastasis, including dissemination of cancer cells into the pleural space." (PMID 35336793, 2022). "Vascular endothelial growth factor D (VEGFD), a member of the VEGF family, is implicated in angiogenesis and lymphangiogenesis, and is deemed to be expressed at a low level in cancers." (PMID 35941690, 2022). "Vascular endothelial growth factor-D (VEGF-D) produced by cancer cells inhibits prostaglandin degradation and results in the dilation of collecting lymphatic vessels, which ultimately promotes cancer metastasis." (PMID 36046433, 2021). "Upregulation of VEGFA indicates neoangiogenesis, low-differentiation and progression in cancer cells, whereas VEGFD plays a key role in neovascularization and formation of lymphatic vessels in cancer tissues." (PMID 31073526, 2019). "In the lymphangiogenic pathway, the VEGFC–VEGFR3 and VEGFD–VEGFR3 axes are required for the dissemination of cancer cells to systemic lymph nodes and distant organs." (PMID 30148861, 2018). "In ovine adenocarcinomas, VEGFR2 and VEGFD mRNA were downregulated in cancers; MMP9, TIMP1 and FGFR2 mRNA were overexpressed as compared to normal lungs." (PMID 29137669, 2017). "Using machine learning algorithms, including RF, SVM, GBM (XGBoost), and DT, the genes CDH3, DKC1, ESM1, MUSTN1, RCC2, TMT1A, and VEGFD were selected as key features from the tissue dataset to best discriminate between cancer and control samples and were used to design the predictive model." (PMID 40425785, 2025). "Except for CHOL and LIHC, VEGFD was down-regulated in 16 cancers." (PMID 37852616, 2023). "Interestingly, the level of VEGFD mRNA was lower in cancers than in normal lungs both in human and ovine adenocarcinomas." (PMID 29137669, 2017). "In agreement with previous observations carried out on cancer cells, AFM revealed that VEGFD increases the stiffness of cultured neurons." (PMID 39158743, 2024). "Across the 33 cancers, VEGFB and VEGFD showed the highest and lowest expression levels, respectively." (PMID 37852616, 2023). "Studies on animal models of cancer progression have reported that tumor cells secrete lymphangiogenic factors, including VEGFA, VEGFC, and VEGFD; induce active metastasis; and promote the circulation of cancer cells into LNs and other sites." (PMID 35626729, 2022). "Protein expression of VEGFA and of its receptor VEGFR2 was almost abolished in cancers while VEGFB and VEGFD mRNA expression were significantly reduced." (PMID 29137669, 2017). "It is also noteworthy that, compared to ASCs-CM, hUCESCs-CM contain lower levels of factors known to participate in cancer progression, such as EGFR, FGF 4 and 9, ICAM3, IL6, IL6R, MCP3 (CCL7), MIF, sgp130 and VEGFD." (PMID 25296979, 2014). "We observed a distinct negative correlation between VEGFD expression and hypoxia across most cancers, but no study has established this finding." (PMID 37852616, 2023). "VEGFC and VEGFD bind to VEGFR3 and activate the downstream signals, which may induce lymphangiogenesis and promote lymph node and organ metastasis in various cancers." (PMID 33128283, 2021).
cancer (continued). "In contrast to CEACAM5 and CXCL17, two markers demonstrated lower levels in the plasma of cancer patients: VEGFR2 acts as a cell-surface receptor for vascular endothelial growth factors (VEGFA, VEGFC and VEGFD), and is involved in angiogenesis in both physiological and pathological conditions." (PMID 31357969, 2019).
adenocarcinoma (5 papers, 2009 to 2017). A common cancer characterized by the presence of malignant glandular cells. "The results were comparable: VEGFA and VEGFR2 patterns of expression were similar; VEGFD, FGF2 were significantly downregulated as in lepidic adenocarcinomas and MMP2 was also significantly downregulated." (PMID 29137669, 2017). "Moreover, mRNA expression VEGFD, FGF2 MMP2, NRP1 and NRP2 was decreased in lepidic adenocarcinomas when compared to the normal lungs." (PMID 29137669, 2017). "On the contrary, we observed decreased mRNA expression of VEGFD, FGF2 and MMP2 and the absence of VEGFR2 proteins in human lepidic adenocarcinomas." (PMID 29137669, 2017).
cardiovascular diseases (4 papers, 2018 to 2024). "Mutations of the following genes can lead to cardiovascular disease: Filamin A, EMD (emerin), LAMP2 (lysosomal-associated membrane protein 2), DMD (dystrophin), TAZ (tafazzin), and VEGF-D (vascular endothelial growth factor D)." (PMID 30459711, 2018).
VEGFD also shares sentences with these, for which no sentence is quoted: colorectal cancer (19 papers); lymphangioleiomyomas (12); lymphedema (11); ischemic stroke (10); Chylothorax (9); pulmonary diseases (9); tuberous sclerosis (9); atrial fibrillation (8); Insulin resistance (7); hepatocellular carcinoma (6); infection (6); pneumothorax (6); colon carcinoma (5); esophageal cancer (5); gastric adenocarcinoma (5); metabolic syndrome (5); cervical cancer (4); glioblastoma (4); myocardial infarction (4); atherosclerosis (3); bladder cancer (3); coronary artery disease (3); endothelial dysfunction (3); glioma (3); hemangioma (3); kidney disease (3); metastasis (3); papillary thyroid carcinoma (3); renal fibrosis (3); age-related macular degeneration (2).
A further 127 diseases each share a sentence with VEGFD in 2 papers or fewer.